SLC39A14 (solute carrier family 39 member 14)
Diseases named in the same sentence as SLC39A14 in open-access papers (continued):
Sharing a sentence is not in itself a finding about the gene and the disease.
colorectal cancer (6 papers, 2019 to 2024). A primary or metastatic malignant neoplasm that affects the colon or rectum. "SRSF1 has been implicated in the alternative splicing of SLC39A14 in colorectal cancer cells." (PMID 36062189, 2022). "RNA sequencing data showed that SLC30A10 expression in colorectal cancer negatively correlates with its functional antagonists SLC39A14 and SLC39A8." (PMID 39596116, 2024). "Likewise, deregulated alternative splicing of SLC39A14 (zinc transporter ZIP14) resulted in low 4A/4B exon ratio both in precursor lesion (adenoma) and colorectal cancer, when it was high in normal colonic tissue." (PMID 31861708, 2019). "Using two model human cancer cell lines (HCT-15 for colorectal cancer and HuTu80 for duodenal carcinoma) we generated HCT-15 and HuTu80 knockout cell lines for the SLC39A14 gene and an HuTu80 knockout cell line for the SLC39A8 gene." (PMID 39596116, 2024). "For instance, SRSF1 is involved in the alternative splicing of solute carrier family 39 member 14 (SLC39A14, zinc transporter) through the Wnt pathway in colorectal cancer cells." (PMID 36062189, 2022).
metastatic carcinoma (6 papers, 2020 to 2024). A carcinoma which has spread from the original site of growth to another anatomic site. "Studies have shown that the expression of the iron metabolism-related gene SLC39A14 (ZIP14) is upregulated in cachectic muscles from rodents and humans with various metastatic cancers." (PMID 36139912, 2022). "Studies have shown that the metal‐ion transporter, solute carrier family 39 member 14 (SLC39A14, also known as ZIP14), is a key mediator of cachexia in metastatic cancers." (PMID 32730698, 2020).
hereditary hemochromatosis (5 papers, 2019 to 2025). An inherited metabolic disorder characterized by iron accumulation in the tissues. "By crossbreeding Slc39a14-deficient mice with mouse models of haemochromatosis (Hfe and Hfe2 mutants), researchers explored the role of Slc39a14 in tissue iron loading." (PMID 38812011, 2024).
liver disease (5 papers, 2016 to 2024). "Unlike SLC30A10 deficiency, SLC39A14 deficiency does not produce liver disease, polycythemia, or EPO excess." (PMID 38652538, 2024).
colon cancer (3 papers, 2015 to 2020). "From the total 244 switches, 10 occur in known cancer drivers, and several others have been associated before with cancer, like CD44, which has been observed to be relevant in colon cancer initiation, and SLC39A14, whose alternative splicing is regulated by WNT in colon cancer." (PMID 25578962, 2015). "The abundance of the different exons of the SLC39A14 gene (also known as zinc transporter ZIP14) shows an uneven balance in normal and tumor tissues in colon cancer patients." (PMID 26113876, 2015).
gastric cancer (3 papers, 2020 to 2024). A primary or metastatic malignant neoplasm involving the stomach. "On the other hand, higher SLC39A14 expression in gastric cancer patients was closely associated with a favorable overall survival." (PMID 38602575, 2024). "SLC39A14 was also reported to be up-regulated, which implied a better OS in gastric cancer patients." (PMID 35371305, 2022). "SLC39A14 has been found up‐regulated in gastric cancer and thus has been considered as a prognostic biomarker." (PMID 32729666, 2020).
iron overload (3 papers, 2023 to 2024). "Especially in hepatocytes and pancreatic acinar cells, ZIP14 (SLC39A14) was identified as the main carrier for NTBI intake during iron overload." (PMID 38397806, 2024).
polycythemia (3 papers, 2017 to 2024). Abnormally high mass or concentration of red blood cells in the blood, either due to an increase in erythropoiesis or a decrease in plasma volume. "This indicated that Slc39a14 is also essential for aberrant expression of several hypoxia-regulated genes and polycythemia in Slc30a10 deficiency." (PMID 38652538, 2024). "Overall, characterization of mice with Slc39a14 and Slc30a10 deficiency indicated that Slc39a14 is essential for development of liver Mn excess, Epo excess, and polycythemia in Slc30a10–/– mice." (PMID 38652538, 2024). "Slc39a14 deficiency corrects liver Epo excess and polycythemia in Slc30a10–/– mice." (PMID 38652538, 2024). "This suggested that SLC39A14-dependent import of Mn into liver drives EPO excess and polycythemia in SLC30A10 deficiency." (PMID 38652538, 2024). "To further investigate the basis of EPO excess and polycythemia in SLC30A10 deficiency, we interrogated SLC39A14." (PMID 38652538, 2024). "In contrast to SLC39A14 deficiency, SLC30A10 deficiency results in polycythemia and excess levels of erythropoietin, a hormone that stimulates RBC synthesis." (PMID 34051234, 2021). "Unlike SLC30A10 deficiency, SLC39A14 deficiency does not produce liver dysfunction, polycythemia, or EPO excess)." (PMID 38652538, 2024). "Mutations in the cellular Mn export protein SLC30A10 lead to Mn excess, dystonia, Parkinsonism, polycythemia, and chronic liver disease, while mutations in the cellular Mn import protein SLC39A14 lead to a similar disease albeit without polycythemia and liver disease." (PMID 28617866, 2017). "(In contrast, unlike SLC39A14 deficiency, SLC30A10 deficiency also leads to liver cirrhosis and polycythemia." (PMID 34051234, 2021). "Unlike SLC39A14 deficiency, SLC30A10 deficiency causes erythropoietin excess and polycythemia, although the link between Mn excess and erythropoietin excess has yet to be firmly established." (PMID 34051234, 2021). "However, given that Slc39a14 deficiency also impacted Mn levels in extrahepatic tissues, we could not formally exclude a role for SLC39A14 in those other tissues in determining EPO excess and polycythemia." (PMID 38652538, 2024).
breast tumor (2 papers, 2016 to 2021). "Statistical analysis of Zn transporter expression indicated that similar to what was observed in breast tumor tissues, basal-like cancer cells also had significantly higher expression of MTs and SLC39A14 and lower expression of SLC39A6, SLC39A9, and SLC39A11 (fold-change >1.5; FDR, p < 0.05)." (PMID 26728511, 2016).
colorectal tumor (2 papers, 2012 to 2017). "Researchers identified alternative splicing of SLC39A14, a divalent cation transporter, in colorectal tumors and found it to be regulated by the Wnt pathway, probably through regulation of splicing factor SRSF1." (PMID 22682314, 2012).
dystonia 1 (2 papers, 2019 to 2025). "Biallelic loss‐of‐function variants in the genes encoding the two Mn transporters, SLC30A10 and SLC39A14, cause autosomal recessive movement disorders termed hypermanganesemia with dystonia 1 (HMNDYT1) and 2 (HMNDYT2), respectively." (PMID 41177175, 2025).
gastric adenocarcinoma (2 papers, 2023 to 2025). "Using The Cancer Genome Atlas (TCGA), we identified SLC39A14-PIWIL2 fusions in stomach adenocarcinoma (STAD) and lung squamous cell carcinoma (LUSC), with breakpoints differing from those in AJHCC007." (PMID 41422314, 2025).
glioma (2 papers, 2023 to 2025). A benign or malignant brain and spinal cord tumor that arises from glial cells (astrocytes, oligodendrocytes, ependymal cells). "Previous studies have shown that the cGMP-PKG signaling pathway plays an important role in glioma, but the correlation between SLC39A14 and the cGMP-PKG signaling pathways in glioma has received little attention." (PMID 37978473, 2023). "Subsequently, we delved deeper into investigating the function of SLC39A14 in glioma and sought to elucidate the precise molecular mechanisms that connected with ferroptosis." (PMID 37978473, 2023). "In the present study, we found that knockdown of SLC39A14 inhibited the proliferation, invasion and migration of glioma cells and promoted apoptosis, which has rarely been reported before." (PMID 37978473, 2023). "In vitro experiments revealed that the knockdown of SLC39A14 significantly inhibited glioma development and promoted erastin-induced ferroptosis." (PMID 37978473, 2023). "Subsequently, ROC curve analysis suggested that the AUC values of WWTR1, STEAP3, SLC39A14, NOTCH2, IREB2, HIF1A, and FANCD2 were all 1.000, indicating their potential as diagnostic biomarkers for gliomas." (PMID 37978473, 2023). "In conclusion, we identify seven ferroptosis-associated genes (SLC39A14, WWTR1, STEAP3, NOTCH2, IREB2, HIF1A, and FANCD2) in gliomas, all of which are highly expressed." (PMID 37978473, 2023). "Survival analysis revealed a significant correlation between the expression of SLC39A14 and the survival of glioma patients." (PMID 37978473, 2023). "Knockdown of SLC39A14 inhibited glioma cell proliferation, migration, and invasion, while promoting apoptosis." (PMID 37978473, 2023). "However, the role of SLC39A14 and the mechanisms regulating ferroptosis in gliomas have been scarcely reported." (PMID 37978473, 2023). "Our research shows that SLC39A14 may play a role in glioma progression by modulating the cGMP-PKG signaling pathway." (PMID 37978473, 2023). "Subsequently, we investigated the mechanisms through which SLC39A14 influences glioma progression." (PMID 37978473, 2023). "In the present investigation, we found that SLC39A14 silencing may promote erastin-induced ferroptosis in glioma by modulating the levels of MDA, Fe2+, GSH, GPX4, NRF2, and SLC7A11, which may further inhibit the progression of gliomas." (PMID 37978473, 2023). "Knockdown of SLC39A14 inhibits glioma cell growth, metastasis and promotes apoptosis." (PMID 37978473, 2023). "Additionally, EdU results showed that silencing SLC39A14 remarkably impeded the proliferation of glioma cells." (PMID 37978473, 2023). "However, the mechanisms of ferroptosis in glioma are complex, and further research is needed for a comprehensive understanding.SLC39A14, a member of the SLC39A family, has transport characteristics." (PMID 37978473, 2023). "Moreover, in both erastin-treated glioma cells, SLC39A14 knockdown significantly enhanced the concentration of MDA, Fe2+ and significantly reduced the levels of GSH.Ferroptosis is characterized by a distinctive mechanism involving GSH depletion and the accumulation of lipid ROS." (PMID 37978473, 2023). "Further experimental exploration is required to establish the correlation between SLC39A14 and the cGMP-PKG signaling pathway and their roles in glioma." (PMID 37978473, 2023). "Seven ferroptosis-related hub genes, namely SLC39A14, WWTR1, STEAP3, NOTCH2, IREB2, HIF1A, and FANCD2, were identified, all of which were highly expressed in glioma." (PMID 37978473, 2023).
ovarian carcinoma (2 papers, 2021 to 2023). A malignant neoplasm originating from the surface ovarian epithelium. "The expression of CYBRD1, LRP2, TFRC, SLC22A17, HEPH, SLC39A14, and PCBP2 involved in iron import was associated with poor OS of ovarian cancer, whereas the expression of LCN2, CP, SLC46A1, STEAP3, and LTF in this process was associated with improved OS in ovarian cancer." (PMID 38186569, 2023).
renal carcinoma (2 papers, 2022 to 2025). A carcinoma arising from the epithelium of the renal parenchyma or the renal pelvis. "In renal carcinoma, circ_001842 strengthens the proliferation, migration and invasion of cancer cells by inhibiting miR-502-5p and increasing the expression of SLC39A14." (PMID 36532744, 2022). "SLC39A14, also called zip‐14, belongs to the SLC39A transmembrane metal transporter family;25 its expression is upregulated in gastric and renal cancer tissues, making it a potential prognostic biomarker." (PMID 40197818, 2025).
bladder cancer (1 paper, 2025). "For example, a pan-cancer TCGA analysis found that tumor overexpression of SLC39A3, SLC39A5, and SLC39A11 was associated with better overall survival after bladder cancer diagnosis, whereas tumor overexpression of SLC39A2, SLC39A8, SLC39A9, and SLC39A14 was associated with poorer survival." (PMID 39789109, 2025).
choroid plexus papilloma (1 paper, 2023). "Support for this possibility is provided by studies using a human choroid plexus papilloma cell line (HIBCPP cells), which showed that ZIP14 is present nearly exclusively in basolateral membrane, and that SLC39A14 knockdown decreases cellular 54Mn accumulation by 44%." (PMID 37482277, 2023).
colorectal adenoma (1 paper, 2022). An adenoma that arises from the colon or rectum. "AS of the cadmium transporter SLC39A14 is associated with colorectal adenoma and carcinoma development." (PMID 35583632, 2022).
generalized dystonia (1 paper, 2018). "We present two siblings with a homozygous missense variant in SLC39A14, manifesting a rapidly progressive generalized dystonia in infancy and hypermanganesemia, similar to a cohort of eight SLC39A14 mutated children reported." (PMID 29382362, 2018).
GM1 gangliosidosis (1 paper, 2025). A rare lysosomal storage disorder characterized biochemically by deficient beta-galactosidase activity and clinically by a wide range of variable neurovisceral, ophthalmological and dysmorphic features. "While GM1 gangliosidosis and PLAN are relatively more common diseases, the total number of reported cases in the literature for SLC6A3, SLC30A10, and SLC39A14 is approximately 50 for each condition." (PMID 40362326, 2025).
lung adenocarcinoma (1 paper, 2023). A carcinoma that arises from the lung and is characterized by the presence of malignant glandular epithelial cells. "The protein expression of SLC3A2, SLC11A2, SLC1A5, SLC16A1, SLC39A7, SLC39A14 in the lung adenocarcinoma cell line A-549 and H1299 is higher than that in the normal lung epithelial cell line Beas-2B." (PMID 37973895, 2023). "The gene expression of SLC3A2, SLC16A1, SLC39A14, SLC39A7, SLC1A5, and SLC11A2 in the lung adenocarcinoma cell line A-549 and H1299 is higher than that in the normal lung epithelial cell line Beas-2B." (PMID 37973895, 2023).
melanoma (1 paper, 2022). A malignant, usually aggressive tumor composed of atypical, neoplastic melanocytes. "For the level of mRNA expression in the TCGA database and melanoma cell lines, SLC39A14, PSMB4, CRELD2, CDKN2A and TIMP1 were higher in SKCM tissues than in normal skin tissues, and NDRG1, ATF3, and JUND had an opposite trend." (PMID 36226170, 2022).
oculogyric crisis (1 paper, 2025). A focal dystonia that is characterized by a prolonged involuntary upward deviation of the eyes. "While certain features like seizures or oculogyric crisis may be found in GLB1 and PTS, or SLC6A3 and SPR, respectively, levodopa response is more inconsistent in GLB1, SLC6A3, SLC30A10, and SLC39A14, and should guide the diagnosis." (PMID 40362326, 2025).
ovarian serous cystadenocarcinoma (1 paper, 2019). A malignant serous cystic epithelial neoplasm arising from the ovary. "Recently using genome-wide methylation data analysis, five-methylation signature (SLC39A14, PREX2, KCNIP2, CORO6, and EFNB1) were reported as novel independent prognostic biomarker for patients with ovarian serous cystadenocarcinoma, which significantly associated with OS of patients." (PMID 31608277, 2019).
Torticollis (1 paper, 2017). Involuntary contractions of the neck musculature resulting in an abnormal posture of or abnormal movements of the head. "Unlike Slc39a14−/− mice, the hepatocyte-specific Slc39a14-knockout mice do not develop torticollis (data not shown), reduced body weight, or neurological deficits, suggesting that dysregulated Mn metabolism in non-hepatic tissues contributes to the phenotype in Slc39a14−/− mice." (PMID 28751976, 2017).
cancer (30 papers, 2011 to 2025). A tumor composed of atypical neoplastic, often pleomorphic cells that invade other tissues. "In contrast, in prostate cancer, low expression of SLC39A14 has been associated with the aggressiveness of malignant tumour and tumour progression." (PMID 32729666, 2020). "SLC39A14-mediated zinc acculation in muscle progenitor cells represses the expression of class I myosin and myocyte enhancer factor 2C and prevents muscle-cell differentiation and induces myosin heavy chain loss, which leads metastatic cancer promoting cachexia." (PMID 32744318, 2020). "SLC39A14 has been found as involved in tumorigenesis of several cancers and has been identified as a novel biomarker for a variety of cancers, which is in agreement with our finding." (PMID 32729666, 2020). "The cancer-specific splicing event of SLC39A14, however, is reported to have high cancer sensitivity." (PMID 21619627, 2011). "SLC39A14 significantly influences cancer prognosis, cellular function, and pathological mechanisms." (PMID 40869935, 2025). "Considering that such opposing findings suggest SLC39A14 may exhibit variable expression patterns and effects on different human cancers, its role in RCC needs to be elucidated." (PMID 32729666, 2020). "We identified a rare case of SLC39A14-PIWIL2 expression in HCC, with evidence of its occurrence in other cancer types." (PMID 41422314, 2025). "Finally, we discovered that the 12 IMRGs expression had significant differences, among which SFXN3, TFR2, TMPRSS6, HMOX1, and LCN2 expressions were elevated in the cancer group, and SCARA5, LTF, STEAP2, SLC39A14, CP, ALAS2, and TF were low expressed in the tumor group." (PMID 37361050, 2023).